SP100 (SP100 nuclear body protein)
Diseases named in the same sentence as SP100 in open-access papers (continued):
Sharing a sentence is not in itself a finding about the gene and the disease.
infection (continued). "The fact that the major latent nuclear antigen LANA, a protein which has been reported to suppress lytic replication of KSHV, induces massive relocalization of soluble Sp100 during a de novo infection suggests that this mechanism serves to promote latency." (PMID 25033267, 2014). "During E30 infection, genes associated with the type I IFN signaling pathway (Isg15, Mx1, Mx2, Sp100, Ifit1, Ifit3, Ifih1, Irf7, Irf9, guanylate-binding proteins 2 [Gbp2], and Stat1) and defense response to viruses (Ddx58, Ddx60, Zbp1, Oas2, Nlrc5, and Eif2ak2) were significantly upregulated." (PMID 36147849, 2022). "Furthermore, keratinocyte depletion of Sp100 using siRNAs results in an increase in HPV18 replication and transcription upon quasivirus infection, demonstrating that Sp100 acts as an intrinsic restriction factor for HPV infection." (PMID 36016419, 2022). "As VSV induced a type I IFN response early in infection and the Sp100 gene is a known interferon-stimulated gene (ISG), whether type I IFN signals the nuclear translocation of Sp100A was investigated." (PMID 36383022, 2022). "Moreover, IE1 also induces degradation of SUMO unmodified Sp100 in a proteasome-sensitive way in late stages of infection." (PMID 34513832, 2021). "More in detail, IE1 has been shown to interact with the Sp100 N-terminal dimerization domain, as deletion of the corresponding 3–152 aa abrogates their association, and infection with mutant HCMV lacking IE1 does not cause loss of Sp100." (PMID 33598438, 2020). "It is attractive to speculate that HPV exploits PML NBs to regulate early transcription, PML protein allowing early transcription to establish infection and delayed Sp100 recruitment helping transition to the maintenance phase." (PMID 30802273, 2019). "Similarly, Sp100 has an anti-viral effect at both early and late stages of infection by hCMV, and HSV." (PMID 28968443, 2017). "We have shown previously that Sp100 represses viral transcription, replication and establishment at early times after infection, and here we extend these findings to show that the differentiation-dependent, productive stage of HPV infection is also limited by Sp100." (PMID 28968443, 2017). "For example, Sp100-mediated repression could promote the shift from early infection to the maintenance phase of infection." (PMID 28968443, 2017). "Therefore, Sp100 foci and viral DNA replication foci interact at late times of infection, concomitant with viral DNA amplification and late gene transcription." (PMID 28968443, 2017). "Identification in our MS dataset of the sumoylated forms of PML and Sp100 as proteins whose abundance is significantly reduced during infection supported the validity of the experiment, as did the lack of change in sumoylated RanGAP1, which is not affected by HSV-1." (PMID 26200910, 2015). "To further investigate this hypothesis, we performed subcellular fractionation of de novo infected EA.hy cells at 72 h post infection and subjected the extracts to western blot analysis with antibodies directed against Sp100, LANA and several marker proteins." (PMID 25033267, 2014). "Our infection studies of Sp100 knock down cells strongly argue for the hypothesis that soluble Sp100 hinders latency establishment rather than suggesting a latency promoting activity of the relocalized protein." (PMID 25033267, 2014). "Likewise, we did not detect a significant reduction in number or size of Sp100-positive foci; instead, we found both number as well as total volume of Sp100 foci to be moderately (but significantly) increased 72 h post infection." (PMID 25033267, 2014).
infection (continued). "To test this, we performed a kinetic analysis to compare the degradation of Sp100, a known ICP0 substrate, in cells infected with the WT virus, the RF-ICP0 mutant, and the new ICP0 mutant at 5 and 10 h post-infection." (PMID 40990523, 2025). "Then, as viral replication and innate immune signaling proceed during infection with ICP0 RF, by 8 hpi, the interaction profile of SLFN5 remains correlated with IFI16, while those of PML, DAXX, and SP100 diverge to cluster with one another." (PMID 40577456, 2025). "In the early stage of infection, HCMV IE1 inhibits PML de novo SUMOylation and degrades Sp100 to initiate viral transcription." (PMID 37058447, 2023). "Since Sp100 was described to interact with HP1 proteins, we analyzed the distribution of HP1α in Sp100-depleted cells after HCMV∆IE1 infection." (PMID 35319461, 2022). "VSV-Sp100A infection in PML−/− and Sp100−/− cells induced significantly higher levels of transcription from RIG-I, OAS-2, IFI16, and IFN-β genes than VSV-GFP did but not transcription from the control gene c-myc." (PMID 36383022, 2022). "Here we show that in the transition from persistent to productive infection in differentiated keratinocytes, HPV again engages the Sp100 component of ND10 bodies." (PMID 28968443, 2017). "Expression of the remaining four genes (PARP9, SP110, SP100 and PRIC285) was unchanged by infection." (PMID 27533247, 2016). "In infected cells the time when US3 starts to express (3–6 h post infection) overlaps with the time when degradation of PML and Sp100 is nearly completed." (PMID 27048561, 2016). "They show that the recruitment of Sp100, an ISG that is a transcriptional repressor and component of NBs, to viral genomes is delayed compared to PML, likely allowing an initial burst of viral transcription to promote infection." (PMID 36016419, 2022). "In summary, Sp100 levels are reduced by VZV ORF61p from the onset of infection but since VZV does not completely disrupt PML-NBs, IFN-response can rise Sp100 protein levels, which are kept dispersed in the nucleoplasm by ORF61p." (PMID 33598438, 2020). "IRF2, RNASEL and SP100 are all upregulated in the CD4 cells of vervet monkey but not of macaques one day post infection." (PMID 31765391, 2019). "Similarly, HCMV targets Sp100 for degradation through its immediate early protein IE1 to prevent their transcriptional repression activity and enhance the early stages of infection." (PMID 30802273, 2019). "We have shown previously that Sp100 (a component of the ND10 nuclear body) represses transcription, replication and establishment of incoming human papillomavirus (HPV) DNA in the early stages of infection." (PMID 28968443, 2017). "During the maintenance stage of infection, levels of viral transcription and replication are not dramatically affected by the Sp100 proteins." (PMID 28968443, 2017). "This experiment revealed significantly more IE2-EYFP positive cells in the absence of PML, hDaxx and Sp100 compared to control cells siC upon infection at an MOI of 0.01 and 0.05." (PMID 26057166, 2015). "Further analysis and functional annotation of all up- and downregulated host genes strongly suggest that the transient increase in Sp100 and PML transcription is due to a pronounced but transient interferon response that is largely ablated at approximately 48 h post infection." (PMID 25033267, 2014). "However, to also formally exclude this possibility, we performed IF analysis for Sp100 and LANA at different time points after de novo infection of SLK cells." (PMID 25033267, 2014). "This conclusion is based on the fact that foci of the episome-binding LANA-protein do not co-localize with PML or Sp100 speckles during the first 24 to 72 hours of a de novo infection." (PMID 25033267, 2014).
infection (continued). "ICP0 initially precisely colocalizes with ND10 at early times upon infection and subsequently mediates the disaggregation of PML-NBs by inducing the degradation of the SUMO-1 modified forms of PML and Sp100, leading to the release and dispersal of other ND10 proteins." (PMID 21994592, 2009). "Since expression of several PML-NB proteins, including Sp100 and PML itself, can be upregulated by IFN treatment, we hypothesized that PML cages may arise due to IFN-mediated increase of PML-NB protein levels during infection with IE1-deleted virus." (PMID 35319461, 2022). "Consequently, many DNA viruses, such as herpes simplex 1 (HSV-1), human cytomegalovirus (HCMV), simian virus 40 (SV40) and adenovirus 5 (ADV5), target PML NBs during primary infection and induce the reorganization and degradation of the residing proteins, including PML protein and Sp100." (PMID 30802273, 2019). "In contrast, viruses like KSHV, for which the default outcome of infection in most if not all cells is latency, encode for vFGARATs that are not capable of degrading PML but affect other components of ND10-NBs like SP100, DAXX or ATRX, and often in a more subtle way than plain degradation." (PMID 29065450, 2017). "Therefore, Sp100 does not affect viral transcription or replication in the maintenance phase of infection." (PMID 28968443, 2017). "Therefore, Sp100 represses the HPV life cycle at both early and late stages of infection." (PMID 28968443, 2017). "In summary, by investigating the in vitro latency model of THP-1 cells, this study provides evidence that PML, hDaxx and Sp100 do not act as critical determinants for the establishment of a quiescent state after infection of monocytes with human cytomegalovirus." (PMID 26057166, 2015). "Similarly, the infection with increasing amounts of the HIV-luciferase virus was enhanced only in the absence of PML but not in the absence of Sp100 or Daxx." (PMID 26703718, 2015). "We conclude that HIRA does not stably colocalize with input vDNA or PML-NBs under infection conditions in which key intrinsic PML-NB restriction factors (PML, Sp100, Daxx, and ATRX;) rapidly entrap and silence vDNA following its nuclear entry." (PMID 30901352, 2019). "After infection of non-differentiated THP-1 cells, we observed that an shRNA-mediated depletion of PML, hDaxx or Sp100 did not affect the initiation of viral IE gene expression." (PMID 26057166, 2015). "Knock-down experiments in primary human cells show that KSHV-infection is restricted by the ND10 components PML and Sp100, but not by ATRX." (PMID 24453968, 2014). "In addition, the shRNA-mediated knockdown of Sp100 and Daxx in THP-1 cells did not affect HIV-GFP infection of these cells." (PMID 26703718, 2015). "Indeed, similar to the observations made in SLK cells, Sp100 became undetectable in low-salt RIPA extracts at 72 (HDF, HUVEC) or 96 h (Ea.hy) post infection in KSHV infected, but not in mock infected cultures (-C and -D)." (PMID 25033267, 2014). "Therefore, PML, hDaxx, and Sp100 could indeed induce silencing of the HHV-6A genome, resulting in a quiescent infection rather than lytic replication." (PMID 30060604, 2018).
tumor (17 papers, 2010 to 2025). "The AC2 cluster was characterised by an overexpression of genes like MMP26, ZNF98 and SP100 associated with tumour promotion." (PMID 39167619, 2024). "A significant difference in SP100 expression was observed among normal, favorable, and unfavorable tumor tissues." (PMID 41458612, 2025). "This is similarly observed in a variety of malignancies where SP100 is degraded and loss of PML-NB integrity is associated with tumor progression and immune evasion." (PMID 41188771, 2025). "Furthermore, breast cancer exhibited high SP100 expression with favorable outcomes, mediated by ETS1 repression and IFN-α modulation, highlighting a tumor-suppressive role for SP100 distinct from other cancers." (PMID 41188771, 2025). "SP140 and SP100 can influence gene programs in macrophages and dendritic cells; thus, they would also likely influence PD-L1 expression as well as pro-inflammatory signaling in the tumor microenvironment." (PMID 41188771, 2025). "SP140’s overexpression may enhance immune responses in the tumor microenvironment, while SP100’s downregulation disrupts differentiation via transcriptional/translational suppression, leading to initiation and progression of tumorigenesis." (PMID 41188771, 2025). "Thus, the results suggest that SP100 serves as both a viral restriction factor, and a tumor immune factor which can be manipulated for therapeutic purposes." (PMID 41188771, 2025). "Furthermore, exploring the role of SP100 as a tumor suppressor in human fibroblasts revealed its function in maintaining cellular senescence and preventing malignant transformation of fibroblasts." (PMID 41188771, 2025). "The results of this study demonstrate that SP100 is significantly low-expressed in tumor tissues." (PMID 41458612, 2025). "In addition, SP100 was discovered to exert its tumor-suppressive effects when it functions as a constituent of PML nuclear bodies." (PMID 38118002, 2024). "Besides NKX2-1, we identified that HNF1B, a previously reported tumor suppressor found in other cancer types, STAT6, and SP100 were inactivated and linked to many silenced enhancers in a subgroup of LUAD." (PMID 32925947, 2020). "However, based on homology, we observed that this region of the protein may mediate interaction with the Sp100, a potent tumor suppressor." (PMID 33435622, 2021). "Homology with SP100 also suggests that SP140 may exert tumor suppressor activity." (PMID 22235315, 2012). "The findings revealed positive correlations between the expression levels of SP100/SP110/SP140 and most tumor-infiltrating immune cells, including activated B cells, Tcm cells, CD8 T cells, and NKT cells." (PMID 37354211, 2023). "Several of these highly expressed genes have growth inhibitory and/or tumor suppressor functions (e.g. XAF1, SP100)." (PMID 34997070, 2022). "We found a striking positive correlation between the SP subfamily of Bromodomain proteins, namely SP100, SP100, SP140, and SP140L, and the estimate score across all analyzed tumor types." (PMID 36614001, 2022). "Here, we demonstrate a significant correlation between SP100, SP110, SP140, and SP140L genes’ expression and immune cell populations in the tumor microenvironment." (PMID 36614001, 2022). "Knockdown of MAML2 significantly affected cell colony formation in vitro, the knockdown of EMP1, IRS2, and SP100 did not affect tumor growth or metastasis." (PMID 40781158, 2025). "Moreover, we found that IBC tumour-infiltrating B cells also presented high levels of immature signals, which was reflected mainly in the significantly high expression of five molecules, CD22, FCRL1, FCRLA, HVCN1, and SP100, in IBC tumour-infiltrating B cells." (PMID 40624675, 2025).
tumor (continued). "The specific isoform miR-455-5p 0|1 likely exerts a tumour-suppressive role, potentially through a non-canonical regulatory interaction with SP100." (PMID 41458612, 2025). "The expression of most BrD members significantly negatively correlated with cancer stemness across many TCGA tumor types, although only for KAT2B, KMT2A, SMARCA2, BAZ2B, SP100 and SP140, the association was highly consistent (regardless of the tumor type)." (PMID 35049055, 2022). "This systematic review underscores the dual oncogenic and tumor-suppressive roles of SP100 family proteins (SP100, SP110, SP140, SP140L) across 25 cancer types, shaped by context-dependent expression patterns, genetic/epigenetic alterations, and possible interactions with tumor microenvironments." (PMID 41188771, 2025).
cancer (13 papers, 2010 to 2025). A tumor composed of atypical neoplastic, often pleomorphic cells that invade other tissues. "Repositioning of either SP100 or TGFB3 towards the nuclear periphery was associated with low Gleason score whereas repositioning towards the interior was a marker of higher Gleason score cancers." (PMID 31681438, 2019). "Since the action of STAT1 varies based on the type of cancer, SP100 tends to guide it toward its growth-limiting role." (PMID 41188771, 2025). "As with Gleason score, in the more highly differentiated cancers (Gleason grades 1-3) SP100 and TGFB3 repositioned towards the nuclear periphery in 100% (5 and 3 cancers, respectively) of the cancers in which these genes repositioned." (PMID 31681438, 2019). "Of a subset of 19 cancer tissues in which both genes were positioned, 10 (52.6%) had differential repositioning patterns for SP100 to that of TGFB3." (PMID 31681438, 2019). "A more peripheral position of SP100 and TGFB3 in the nucleus, compared to benign tissues, is associated with low Gleason score cancers, whereas more internal positioning correlates with higher Gleason scores." (PMID 31681438, 2019). "Despite the fact that low Gleason score cancers represents fairly well differentiated tissues there were distinct positioning patterns for SP100 and TGFB3 between low Gleason score cancers and benign disease, which are considered differentiated tissues." (PMID 31681438, 2019). "Mechanistic studies targeting SP140’s immune pathways (e.g., PD-L1, TRIM22) and SP100’s DNA repair functions in underrepresented cancers (e.g., BLCA, OSCC) could refine therapeutic applications." (PMID 41188771, 2025). "Yet as SP100 levels decrease, STAT1 is suppressed, which causes uncontrolled division of cells and may result in traits like cancer." (PMID 41188771, 2025). "Interestingly, we found four genes (FXR1, RAD50, SP100, SMC6) mutated in 50% of the G1 LS-cancer samples, with the latter three belonging to the APB branch of the ALT-TMM pathway." (PMID 31750255, 2019). "Gene Ontology (GO) annotation for molecular function, biological processes and Reactome Pathways indicated that SP100 and USP45 are involved in DNA repair while ZNF534 is involved in DNA-templated regulation of transcription, making them good candidate cancer predisposing genes." (PMID 30947698, 2019). "After RAYYAN-assisted deduplication and screening, studies analyzing SP100, SP110, SP140, or SP140L alterations in human cancers (excluding cell lines studies) were included." (PMID 41188771, 2025). "The Speckled Protein 100 (SP100) family, comprising SP100, SP110, SP140, and SP140L, has emerged as a critical player in cancer biology due to their roles in transcriptional regulation, chromatin modification, and immune signaling." (PMID 41188771, 2025). "In contrast, SP100 and TGFB3 were in a more internal position in 83.3% (5/6) and 75.0% (3/4), respectively, of the Gleason score 7 and higher cancers in which they repositioned." (PMID 31681438, 2019). "SP100 was more internally positioned in 80% (4/5) of Gleason grade 4 and 5 cancer in which SP100 repositioned and TGFB3 was more internally positioned in 66.7% (2/3) of the Gleason grade 4 and 5 cancers in which TGFB3 was repositioned, compared to the PND." (PMID 31681438, 2019). "For one cancer sample, both genes were repositioned, compared to their PND, but they relocated in opposite directions, with SP100 being more peripherally positioned, while TGFB3 was more internally positioned." (PMID 31681438, 2019). "Both SP100 and TGFB3 shifted to a more peripheral position in 100% of the low Gleason score cancers in which these genes showed an altered radial position." (PMID 31681438, 2019). "Both SP100 and TGFB3 contributed to the increased proportion of cancer specimens with repositioning events." (PMID 31681438, 2019).